ENSG00000274721
Gene: Miscellaneous RNA gene on chromosome 5 (142,318,047 to 142,318,167, forward strand). Ensembl gene ENSG00000274721.
Gene Ontology:
Cellular component: cytoplasm